IL17A (interleukin 17A)
Diseases named in the same sentence as IL17A in open-access papers (continued):
Sharing a sentence is not in itself a finding about the gene and the disease.
infection (continued). "Another finding was that IL-17A amplifies mammary epithelial cells (MECs) responses to infection." (PMID 33059767, 2020). "Enhancement of the IL-17A-mediated immune response by TJ-41 may contribute to additional host defenses against infection, and this should be addressed in future studies." (PMID 33194807, 2020). "However, the IL-17A levels were restored at 45 dpi and were lower than those of healthy animals at 60 dpi in the low-dose infection group." (PMID 32085808, 2020). "Similarly, prior research has shown that γδ T cells also respond during early infection with IL-17A production after direct stimulation of their TCR and without restriction of MHC activation." (PMID 32258066, 2020). "More specifically, as an immunomodulatory nutrient, glutamine regulate tight junction proteins (occludin, claudin-1, and zona occludens-1), controls chain reactions of cytokines such as TNF-α and IL-17A, and increases local secretory IgA (sIgA) production for preventing infection." (PMID 33143293, 2020). "It has been established that IL-17A contributes to the defense of the MG against infections." (PMID 33059767, 2020). "IL-17A-mediated inflammation is required for host protection and survival against infection." (PMID 32849528, 2020). "From the transcriptomic analysis of bovine immune cells (PBMCs), it was suggested that infection through the epithelial cells elicited prolonged Th17-derived immune response, as indicated by upregulation of IL-17A, IL-17F and RORC until 120 h p.i., compared to directly infected PBMCs." (PMID 33273606, 2020). "IL-17A protects against inflammation during pathogen infection." (PMID 32477272, 2020). "We measured TNF-α, IL-6, IFN-γ, IL-17A and IL-10 after an experimental intravenous infection with S. suis serotype 2 in vivo, and analyzed whole blood, peripheral blood mononuclear cells (PBMC) and separated leukocytes to identify the cytokine-producing cell type(s)." (PMID 31947746, 2020). "During K. pneumoniae infection, IL-17A plays a crucial role in host defense against the infection." (PMID 32973776, 2020). "Thus, IL-17A plays a pivotal role in prevention of infection progression and related infectious complications." (PMID 32849528, 2020). "The analysis showed that secretion of IL-17a was significantly higher in group T2 than group T1 at 120 h p.i. even though concentration of IL-17a in both test groups was significantly higher than non-infection control at 72 h and 120 h p.i.." (PMID 33273606, 2020). "Notably, later in infection, once the type-2 response was established, IL-17A limited the magnitude of the type-2 response." (PMID 32636457, 2020). "Thus, the decrease in levels of IL-1RA and increase of IL-17A in patients who received NAC therapy, shows a protective factor of susceptibility to infection." (PMID 33613521, 2020). "Similarly, IL-17A has also been suggested to facilitate the infection of coxsackievirus B3 by decreasing splenic CD8+ T cell numbers and cardiac IFN-γ production and Theiler’s murine encephalomyelitis virus by up-regulating anti-apoptotic molecules." (PMID 33304351, 2020). "The biological role of IL-17A in primary DENV infections could be very different that in secondary infections." (PMID 33322218, 2020). "However, the levels of IL-17A were significantly higher than the proportion of the Th17 cells, and the changes of Th17 cells in lower infection doses were significant than higher infection doses." (PMID 32085808, 2020). "Interestingly, patients with prolonged viral RNA shedding demonstrated lower levels of IL‐1β and IL‐17A during the acute phase of infection." (PMID 32742654, 2020). "During the infection caused by different microbial agents, very similar profiles of the human innate immune response are observed including secretion of IL-1α, IL-8, and IFN-α, and suppression of superoxide dismutase, IL-1Ra and IL-17A release." (PMID 32751625, 2020).
infection (continued). "Thus, consistent with superior expression of PPARy inCCR6+ Th17/Th1Th17-polarized versus CCR6-Th1-polarized T cells, T0070907 acted onCCR6+ T cells to upregu-late IL-17A production and limit HIVde novo infection by mechanisms including CCR5down-regulation." (PMID 33089034, 2020). "In addition, I3C treatment reduced the inflammatory response to Cr infection by maintaining anti-inflammatory cytokine IL-22 mRNA levels while reducing expression of other pro-inflammatory cytokines including IL17A, IL6, IL1β, TNF-α, and IFN-γ." (PMID 33076301, 2020). "Similarly, levels of the pro-inflammatory mediator IL-17A were increased significantly in children with microscopic and submicroscopic infections compared to controls (p = 0.027 and p = 0.027, respectively)." (PMID 33281757, 2020). "Through the AHR expression MPA, may potentially decrease immune function by decreasing T cell IFN-γ and IL-17A production, thereby influencing certain aspects of infection progression." (PMID 31001262, 2019). "Taken together, we show in a mouse TB model that infection with highly virulent clinical Beijing- and EAI-strains is associated with influx of B-cells and elevated IL-4 levels in the lungs, while less virulent H37Rv bacteria induce T-cell influx and higher IFN-γ and IL-17a levels at peak infection." (PMID 31882653, 2019). "Additionally, in mice model, it has been reported that in vivo administration of IL-17A moderately delays time of death from lethal infection of Francisella tularensis live vaccine strain." (PMID 30804945, 2019). "It is possible that IL-17RC expression could also be upregulated in human neutrophils under our experimental settings, i.e., pretreatment with IL-17A for 0.5 h and infection with live P. aeruginosa in the presence of human serum." (PMID 30455194, 2019). "In some studies, H1N1 and H7N9 patients with severe infection showed elevated IL-17A serum levels, and it was proposed that IL-17A might exacerbate lung damage and contribute to the pathogenesis of disease." (PMID 31061831, 2019). "Several studies reported the upregulation of IL-17A during infections in both mice and cattle." (PMID 31222079, 2019). "Furthermore, uncontrolled infections with BCG or Mtb were reported in individuals with defects in IL17A and IL17F production." (PMID 31616423, 2019). "It is not clear whether it is the number difference of cell populations or the expression difference of genes on a per-cell basis induced by the infection of P1 or P150 that contributes to the difference in IL-17A or IFN-γ levels." (PMID 31466385, 2019). "Also in experimental Nocardia brasiliensis mycetoma, IL-17A was found to be increased mainly at the beginning of the infection, at the time the N. brasiliensis mycetoma granuloma is formed." (PMID 31295246, 2019). "Of note, the frequencies of small intestinal CD4+ effector cells expressing RORγt+ and IL-17A+ remained stable upon infection in both mouse lines despite significantly higher proportions of siLP Th17 cells expressing the proliferation marker Ki-67 in infected C57BL/6 mice." (PMID 31889073, 2019). "IL-17A was the only cytokine detected following infection with all strains, including RH." (PMID 30901349, 2019). "As a corollary, augmented IL-17A early during infection might drive the differentiation of naïve T cells into Th17 cells in the later stages of coinfection." (PMID 31107882, 2019). "A recent paper by Erdmann and colleagues describes the ability of IL-17A to contribute to the expansion of IFN-γ-, IL-2- and TNF-secreting multifunctional T cells in IL-27Rα−/− mice, and that the level of IL-17A induction is essential for the accumulation of these cells during infection." (PMID 31736982, 2019). "Furthermore, IL-17A can partially facilitate A549 cell infection by the PR8 strain and PR8-infected IL-17A knock-out mice consistently exhibited decreased weight loss and reduced lung immunopathology, as compared to controls." (PMID 31681209, 2019).
infection (continued). "However, IL-17A and IL-17F expression levels were higher at all time points post-infection in duck spleens." (PMID 31519917, 2019). "IL-17A could be essential for protection from infection in the conditions with low pneumococcal-carriage density." (PMID 31882693, 2019). "In our study, gp43 stimulated PMNs to produce IL-17A only after blocking TLR4, suggesting that gp43 might take advantage of the TLR4/TLR2 interactions during IL-17 production to control inflammatory reactions during an active infection." (PMID 31886295, 2019). "After 28 days of infection, there were few IL-17A+ cells in the ears of all infection groups." (PMID 31107882, 2019). "Note that elimination of IL-17A or IFN-γ by intravenous injection of anti-IL-17A or anti-IFN-γ antibody did not have a significant impact on the survival of Sta-V5-vaccinated mice subjected to lethal challenge by S. aureus in a blood infection model." (PMID 31484738, 2019). "During ETBF-infection, IL-17A is produced by γδ T cells and Th17 cells." (PMID 31540059, 2019). "The results of in vitro infection experiments suggested that compared with mock-infected cells, the frequencies of these two groups of cells and IL-17A levels were reduced at all assessed time points postinfection with H7N9, substantiating the findings for acute-phase H7N9 patients." (PMID 31061831, 2019). "No significant regulation of genes encoding IL-17/C2, IL-17A/F2, and TNFα was observed for any of the tissues during the infection." (PMID 31220151, 2019). "To corroborate our flow cytometry data on the relative abundance of TH1, TH2 and TH17 cells using another independent methodology, we estimated the relative abundance of IL-4, IFN-γ and IL-17A transcripts in RNA extracted from splenocytes at 6 and 8 weeks post infection." (PMID 30653492, 2019). "IL-17A is mainly produced by γδ T cells during L. monocytogenes infection to promote innate and adaptive immune responses, and it promotes host function of effective elimination of infection by producing cytokines and CXC chemokines." (PMID 30116753, 2018). "Low IL-17A levels in sera are maintained by γδT cells in emergencies such as infection." (PMID 30134914, 2018). "Especially, IL-17A, which is largely produced by γδ T cells, could slow down the course of diverse pathogen infections." (PMID 30116753, 2018). "Interestingly, blocking IL-17A or knocking out the receptor in mice, decreased neutrophil recruitment, increased recovered CFUs, and prolonged infection." (PMID 30524442, 2018). "The levels of PPD-B-induced IL-17A (mRNA and protein) could be used to differentiate M. bovis-infected calves from uninfected ones for 6 to 30 weeks post-infection." (PMID 29560355, 2018). "Thus, increased production of IFN-γ and IL-17A in fbp1Δ mutant yeast-infected mice contributes to pulmonary control of infection." (PMID 29317510, 2018). "There are few reports that address the importance of IL-17A profile after infection by MRSA." (PMID 29590259, 2018). "Taken together, this study investigates the role of IL-17A during L. sigmodontis infection and shows that IL-17A influences worm development through the dampening cellular responses in the site of infection and plays an important role in host immunity against this filarial nematode." (PMID 29931394, 2018). "Furthermore, IL-17A was proven to be essential in host protection against Trypanosoma cruzi, during the acute phase of infection, being the hosts B cells the major sources of IL-1761,67." (PMID 30072701, 2018). "Our study reveals that infected IL-17A-deficient C57BL/6 mice present reduced worm burden on days 7 and 28 p.i. but had longer adult worms on day 28 p.i. in the thoracic cavity (TC), the site of infection." (PMID 29931394, 2018). "As for TNF-α, the IL-17A and IL-22 increases were likely related to the magnitude of the bacterial burden and stimulus, and they were apparently unable to improve the course of infection." (PMID 30045763, 2018).
infection (continued). "However, following infection, we observed significantly elevated levels of IL-1β, IL-2, IL-3, IL-5, IL-6, IL-10, IL-17A, MIP-1α, MIP-1β, KC, transforming growth factor β (TGF-β), G-CSF, and GM-CSF in HO-1−/− mice compared to HO-1+/+." (PMID 30428359, 2018). "A high serum IL-17A level might be considered to indicate the possibility of an infection in relation to LCH." (PMID 30134914, 2018). "WT-infected DCs displayed an increased proportion of Th17 cells and secretion of IL-17A as compared to the uninfected DCs, whereas the increased in Th17 cell responses and secretion of IL-17A observed following by WT infection were significantly reduced in DCs infected with the rtxA mutant strain." (PMID 30283443, 2018). "IL-17A and IL-17F are produced in mice upon infection, and deletion or depletion of these cytokines or their receptor consistently leads, in different models, to reduced survival and augmented tissue damage, accompanied by an enhanced pro-inflammatory response." (PMID 30197647, 2018). "IL-17A peaked at 12 hours in BALF with TIGR4 but was delayed to 24 hours following SRL1 infection." (PMID 29813133, 2018). "Consistent with the lack of an eosinophilic response, IL-5 and IL-13 levels were not significantly elevated in the PVM-infected RAGE deficient mice (p=0.7016 and p=0.9973) Levels of IL-17A were also not elevated in RAGE deficient mice upon infection with PVM." (PMID 28099113, 2017). "We demonstrate that aprepitant treatment attenuates B. burgdorferi-induced elevations in CCL2, CXCL13, IL-17A, and IL-6 gene expression in dorsal root ganglia, spinal cord, and/or cerebrospinal fluid of rhesus macaques at 2 to 4 weeks following intrathecal infection." (PMID 28202084, 2017). "However, the proportion significantly increased to 3% post-infection, suggesting that B cells also contributed to the higher levels of IL-17A in infected mice." (PMID 28732522, 2017). "To confirm that eosinophils make IL-23p19 and IL-17A and to assess the intracellular location of these cytokines, we performed confocal microscopy on cells obtained by bronchoalveolar lavage 8 and 54 hours post-infection with A. fumigatus." (PMID 28095479, 2017). "Thus, B cells were the main producers of IL-17A during the acute infection with T. cruzi, and B cell-intrinsic production of IL-17A was critical for the protective response to this pathogen." (PMID 29209313, 2017). "The IL-17A in immune WT mice may enhance neutrophil and macrophage infiltration, effectively eliminating the infection in the nasopharynx." (PMID 28659923, 2017). "In parallel with significantly elevated plasma levels of IL-17A, IL-6 as the major activating cytokine of Th17 cells also revealed significantly increased plasma levels in patients with a fungal colonization, respectively infection." (PMID 28820494, 2017). "As one of the most crucial proinflammatory cytokines, IL-17A plays an important role in host defense against pathogen infection by stimulating cytokines (TNF-α, GM-CSF, etc) and chemokines (CXCL1, CXCL2, IL-8, etc) expression leading to neutrophil expansion and chemotaxis." (PMID 28035060, 2017). "An increase in IL-17A gene expression following infection is particularly interesting since cell signaling mediated by this cytokine plays a key role in regulating the expression of other inflammatory mediators, such as IL-6, via a mechanism that involves NF-κB-mediated transcription." (PMID 28202084, 2017). "A CSF pro-inflammatory response consists of an interplay of Th1 (IFN-γ and IL‐6), Th2 (IL‐4 and IL‐10) and Th17 cytokines (IL‐17A) and has been shown to be highly predictive of increased macrophage activation, rapid clearance of infection and consequently better survival in patients with CM." (PMID 28486489, 2017). "The concentration of IL-1β and IL-23 in the BALF was significantly improved at the early stage of infection, which might promote the secretion of IL-17A by γδT cells." (PMID 28912779, 2017).
infection (continued). "V3000 infection uniquely modulated several inflammatory signaling pathways such as IL-2, IL-4, IL-8, IL-9, IL-12 and IL-17A along with the unfolded protein response, gap junction signaling, crosstalk between DCs and NKCs, interferon and JAK/Stat signaling pathways." (PMID 28446152, 2017). "Interestingly, the induced infection was followed by an increase in the production of IL-17A in the WBA for both immunized groups." (PMID 28611405, 2017). "We observed that butyrate-treated mice challenged with C. rodentium showed differing increases in gene expression of cytokines involved in the clearance of infection (Il17A, Tnfα), the reduction of mucosal inflammation (Tgfβ, Il10), and the improvement of host barrier function (Muc2, Relmβ, Tff3)." (PMID 28861518, 2017). "The percentage of IL-17A+/Vγ2 T cells changed following infection (P < 0.001)." (PMID 28507072, 2017). "During the infections with many bacteria, such as Mycobacterium tuberculosis, Escherichia coli, and Mycobacterium bovis, γδ T cells may become the dominant IL-17A-producing cells, over Th17 cells." (PMID 28377603, 2017). "We found that IL-17A RNA expression increased with the extension of the infection." (PMID 29403160, 2017). "Furthermore, intranasal administration of recombinant IL-17A to antibiotic-treated mice rescued defects in respiratory GM-CSF production during infection with either K. pneumoniae or S. pneumoniae." (PMID 29142211, 2017). "Schedule of treatment with anti-IL-17A mAb was set-up from 10 days post infection to distinguish IL-17A contributions to the lung pathology during advanced P. aeruginosa chronic infection from those determined at the early/acute phase of infection in IL-17a−/− mice." (PMID 27189736, 2016). "The minimal effect of anti-IL-17A treatment on Ccl2 and rather a slightly decreased gene expression of Zc3h12a in lung tissue at day 28, suggest a dispensable role for IL-17A at this stage of the infection." (PMID 27853279, 2016). "Transfer of B-1a-derived natural antibodies rescued Il17a-/- mice from otherwise lethal infections." (PMID 26735852, 2016). "Nevertheless, the serum levels of IL-17A were not only generally maintained at higher levels in the mutant-infected mice when compared to WT bacterium-infected animals at an early infection stage (e.g., day 1), but were also sustained longer in the mutant-infected mice at the later infection stages." (PMID 27891321, 2016). "IL-17A was almost undetectable in both mouse groups during the infection." (PMID 27650379, 2016). "In mice consuming the WB-enriched diet, the expression of the Th17 cytokine, Il-17A was lower than mice consuming the RS-enriched and CN diets during peak infection, and by late infection, these mice exhibited the lowest expression of Th1 (Il-1β, Ifnγ, Tnfα) cytokines." (PMID 28031748, 2016). "In addition, a larger production of IL-17A by lymph node cells was found at 8 weeks of infection, which correlated with the larger neutrophil infiltrate." (PMID 27056545, 2016). "While increased recruitment of neutrophils to the site of infection may be beneficial, we hypothesized that IL-17A signalling also could be involved in neutrophil viability." (PMID 27723804, 2016). "Mucosal infection with an M1 GAS strain induced a strong antigen-specific Th17 response in cells isolated from nasal-associated lymphoid tissue of C57BL/6 mice, with CD4+ cells producing IL-17A, whereas intravenous and subcutaneous infection produced IFN-γ secreting cells." (PMID 27241677, 2016). "Furthermore, the expression of IL‐17A in the early phase of infection is necessary for the Th1 type delayed‐type hypersensitivity response and optimum granuloma formation." (PMID 27980775, 2016). "In HIV monoinfected persons, HIV-specific, IL-17A-producing CD4+ T cells have been detected in early infection and have been proposed to be virus-specific T cells aberrantly primed as a result of microbial translocation due to HIV-related depletion of gut CD4 T cells." (PMID 27124305, 2016).